CXCL2 (C-X-C motif chemokine ligand 2)
Diseases named in the same sentence as CXCL2 in open-access papers (continued):
Sharing a sentence is not in itself a finding about the gene and the disease.
bladder cancer (18 papers, 2018 to 2024). "Several chemokines within the CXCL family, such as CXCL1, CXCL2, CXCL5, CXCL8 (IL-8), and CXCL12, also play a crucial role in the recruitment of myeloid cells and TAM in bladder cancer, and are associated with tumor grading, staging, and metastasis." (PMID 39606239, 2024). "In vitro chemotaxis experiments demonstrated that bladder cancer cell line J82 induced MDSC migration via the CXCL2/IF-CXCR2 signaling pathway." (PMID 39606239, 2024). "The CXCL5/CXCL2 axis also promotes bladder cancer cell migration by upregulating MMP2/MMP9, which is an Akt-dependent pathway." (PMID 37373052, 2023). "In bladder cancer, CXCL2 induces the migration of myeloid-derived suppressor cells (MDSCs) into the tumor microenvironment." (PMID 36290882, 2022). "In bladder cancer, tumor cells secreted CXCL2-stimulating nuclear factor kappa B (NF-κB) pathways in MDSCs to induce MDSC accumulation in the TME via CXCL2-CXCR2 signaling." (PMID 34527668, 2021). "Previous studies have revealed that elevated expression of CXCL2 in tumor tissues is related to advanced stages and worse prognosis of bladder cancer." (PMID 34269159, 2021). "Chemokine CXCL2 was reported to be related with prognosis of bladder cancer, but its role in the progression of osteosarcoma was still unclear." (PMID 32974202, 2020). "C-X-C motif chemokine ligand 2 (CXCL2) was demonstrated to be up-regulated in many types of cancer such as chronic lymphocytic leukemia and bladder cancer." (PMID 30662454, 2018). "For example, CXCL2 secreted by bladder cancer cells participate in recruiting myeloid-derived suppressor cells and is correlated with a poor prognosis." (PMID 30158589, 2018). "Some researchers have reported that the expression of CXCL1 and CXCL2 is correlated with tumor size, metastasis, and decreased overall survival in breast, gastric, colorectal, hepatocellular, and bladder carcinoma patients." (PMID 29703902, 2018). "CXCL2 can promote the recruitment of MDSC and is associated with the prognosis of bladder cancer." (PMID 33708242, 2021). "CXCL2 increased bladder cancer progression by recruiting myeloid-derived suppressor cells." (PMID 32547867, 2020). "The up-regulation of CXCL2 could enhance the cell survival of lymphocytic leukemia and it was correlated with poor prognosis of bladder cancer." (PMID 30662454, 2018). "In bladder cancer cells, activation of CXCL2/MIF-CXCR2 signaling aggravated MDSC accumulation and expansion in the bladder cancer TME." (PMID 36042480, 2022).
colorectal cancer (18 papers, 2015 to 2025). A primary or metastatic malignant neoplasm that affects the colon or rectum. "CXCL2 expression was higher in colorectal cancer tissues than in adjacent normal tissues and was associated with the degree of invasion and lymph node metastasis of colorectal cancer." (PMID 38021148, 2023). "CXCL2: Significantly overexpressed in colorectal cancer, involved in tumor initiation, development, and angiogenesis." (PMID 39546375, 2024). "METTL3 facilitates pulmonary metastasis of colorectal cancer by targeting the m6A-Snail-CXCL2 axis to recruit M2-type immunosuppressive macrophages." (PMID 38605400, 2024). "SNAIL and CXCL2 have different mechanisms in promoting the progression of colorectal cancer and lung metastasis." (PMID 35541899, 2022). "Colorectal CSCs secrete CXCL1 and CXCL2 to attract neutrophils, which promoted tumorigenesis of colorectal cancer cells via interleukin-1β." (PMID 31998654, 2019). "Additionally, colorectal cancer cells expressing METTL3 recruit M2-type macrophages by secreting CXCL2." (PMID 38605400, 2024). "The expression of SNAIL could induce epithelial-to-mesenchymal transition and lung metastasis of tumors secreting CXCL2 to promote the invasion of M2-type immunosuppressed macrophages in colorectal cancer." (PMID 38232115, 2024). "CXCL2 (alias Gro2) shows elevated expression in colorectal cancer already in premalignant lesions and in CRC and it could accelerate tumor cell growth by inducing cell proliferation in a mouse implantation model." (PMID 26208990, 2015). "Conversely, the suspected dysplasia was characterized by the expression of CXCL2/3 (inflammatory markers), LCN2 (a secretory protein potentially acting as a tumor suppressor in colorectal cancer), and SOD2 and NCOA7 (stress response genes)." (PMID 40667282, 2025). "METTL3 promotes epithelial-mesenchymal transition in colorectal cancer by m6A modification of SNAIL mRNA, where SNAIL enhances the secretion of CXCL2 through the NF-κB pathway." (PMID 38605400, 2024). "For example, in colorectal cancer tissue, CXCL1, CXCL2, CXCL3, CXCL5, CXCL8, and CXCL11 were highly expressed, while CXCL12, CXCL13, and CXCL14 were little expressed." (PMID 36612163, 2022). "High mobility group box 1 (HMGB1), released from GSDMC‐mediated pyroptotic tumor cells, upregulates CXCL2 expression in adjacent tumor cells, thereby recruiting myeloid‐derived suppressor cells (MDSCs) into the tumor microenvironment (TME) to promote colorectal cancer progression." (PMID 40213993, 2025). "Moreover, colorectal cancer cells expressing METTL3 recruit M2 macrophages by secreting CXCL2, a finding confirmed through in vitro experiments and in vivo experiments with METTL3-silenced colorectal cancer cells." (PMID 38605400, 2024).
periodontitis (18 papers, 2020 to 2026). An acute or chronic inflammatory process that affects the tissues that surround and support the teeth. "In this disorder, periodontitis has been associated with a marked upregulation of IL-17A and other related cytokines, as well as chemokines responsible for neutrophil recruitment (CXCL2, CXCL5)." (PMID 41462866, 2025). "The present study also revealed that periodontitis is associated with increased IL-6 and CXCL2 levels in human and rat gingiva." (PMID 34024010, 2022). "The gene expression analyses of the gingiva of rats with experimental periodontitis and/or orthodontic tooth movement also showed that periodontal inflammation was associated with an increase in IL-6 and CXCL2 levels at 8 day." (PMID 34024010, 2022). "We detected a significant increase in mRNA levels of Interleukin (IL)-1β, IL-17 and the chemokines Cxcl1 and Cxcl2 which are important neutrophil chemoattractants (corresponding to Cxcl8 in humans) in gingival tissue derived from CD73-deficient animals with periodontitis when compared to the WT." (PMID 38152410, 2023). "Periodontitis caused an increase in gingival levels of IL-6 and CXCL2 in the animal model." (PMID 34024010, 2022). "Among chemokines, CXCL2 was prioritized because it showed consistent upregulation across bulk periodontitis transcriptomes and IBD myeloid states, and it aligned with prominent IL-1β-chemokine signaling routes inferred from intercellular communication." (PMID 41624856, 2026). "Our scRNA-seq analysis revealed that macrophages expressed Ccl2, Ccl9, Cxcl4, and Cxcl6, and neutrophils expressed Ccl3, Ccl4, Ccl6, Cxcl2, and Cxcl3 throughout periodontitis development." (PMID 38015204, 2023). "In the present study, we investigated the individual and combined effects of periodontitis and orthodontic tooth movement on IL-6 and CXCL2." (PMID 34024010, 2022). "In contrast, however, immunostaining against IL-6 and CXCL2 proteins was more pronounced in the biopsies of periodontitis patients." (PMID 34024010, 2022). "Our results showed that gavage of periodontitis saliva increased the expression of inflammatory factors, including Il-1β, Tnf-α, Cxcl1, Cxcl2, and Ccl2, in the ischemic brain in mice." (PMID 35663549, 2022). "A recent study revealed that periodontitis enhanced gingival levels of IL-6 and CXCL2 in an animal model." (PMID 35478496, 2022). "The gene expression analysis by real-time PCR revealed that the mRNA levels of IL-6 and CXCL2 were significantly (p<0.05) higher in gingival biopsies from periodontitis patients than in the gingiva of periodontally healthy individuals." (PMID 34024010, 2022). "The IL-6 and CXCL2 levels were also studied in human gingival biopsies from periodontally healthy and periodontitis subjects by RT-PCR and immunohistochemistry." (PMID 34024010, 2022). "The aim of this in vitro and in vivo study was to investigate the interaction of periodontitis and orthodontic tooth movement on interleukin (IL)-6 and C-X-C motif chemokine 2 (CXCL2)." (PMID 34024010, 2022). "So far, we are not aware of any other study dedicated to the combined effect of periodontitis and orthodontic tooth movement on CXCL2." (PMID 34024010, 2022). "The aim of this in vitro and in vivo study was to investigate the single and combined effects of periodontitis and orthodontic tooth movement on IL-6 and CXCL2." (PMID 34024010, 2022). "Additionally, periodontitis induced elevated gingival IL-6 and CXCL2 levels in a rat model of tooth movement." (PMID 40724937, 2025). "Elevated IL-6 and CXCL2 gingival levels were also found in human periodontitis." (PMID 34024010, 2022). "In the present study, CXCL2 was also increased in human and rat gingival biopsies of periodontitis." (PMID 34024010, 2022). "Enhanced IL-6 and CXCL2 levels have also been detected in the gingiva in human periodontitis." (PMID 35478496, 2022). "Similarly, increased gingival IL-6 and CXCL2 levels were observed in human periodontitis." (PMID 40724937, 2025).
periodontitis (continued). "Moreover, chemokines such as CXCL8, CXCL10, CXCL12, and CCL5 accumulate in the crevicular fluid of periodontitis patients and their source might be attributed to fibroblasts at least for CXCL2, CXCL3, CXCL8, CXCL9, CXCL10, CXCL12, and CXCL16." (PMID 37762294, 2023). "Further experiments should then clarify whether the effects of periodontitis and/or orthodontic tooth movement on IL-6 and CXCL2 can be simulated in vitro and, if so, by what mechanism the effects of periodontitis and/or orthodontic tooth movement on these inflammatory mediators are realized." (PMID 34024010, 2022). "Since IL-6 and CXCL2 have pro-inflammatory and chemotactic activities that are increased in periodontitis, the first aim was to clarify whether IL-6 and CXCL2 are increased in gingival biopsies from periodontitis patients compared with periodontally healthy subjects." (PMID 34024010, 2022). "Salicin treatment significantly inhibited the expression of CXCL1, CXCL2 and CXCL5 in the gingival tissue of WT-periodontitis mice, while these inhibitory effects of salicin were abolished in the Gnat3-/- periodontitis mice." (PMID 38605968, 2024). "The effect of periodontitis and/or orthodontic tooth movement (OTM) on alveolar bone and gingival IL-6 and CXCL2 expressions was studied in rats by histology and RT-PCR, respectively." (PMID 34024010, 2022). "The enrichment of TNFRSF21+ fibroblasts with high expression of CXCL1, CXCL2, CXCL5, CXCL6, CXCL13, and IL24 was detected in patients with periodontitis compared to healthy individuals." (PMID 35154475, 2022). "Previous studies have reported heterogeneity in gingival fibroblasts in periodontal tissues, with four subsets significantly altered in periodontitis: Fib 1.1 (CXCL1, CXCL2, CXCL13); Fib 1.2 (APCDD1, IGFBP2, MRPS6); Fib 1.3 (APOD, GSN, CFD); and Fib 1.4 (TIMP3, ASPN, COL11A1)." (PMID 40801798, 2025). "Moreover, PRF membranes increased chemokines CCL2, CCL7, CXCL2, and CXCL3, most of which are highly expressed in periodontitis fibroblasts." (PMID 39120336, 2024). "In healthy tissue, however, oral commensal bacteria are associated with the selective expression of CXCL2 but not CXCL1, suggesting CXCL1 is a lead chemokine in oral epithelial cells for periodontitis." (PMID 37762294, 2023). "In contrast to periodontitis, orthodontic tooth movement did not increase the IL-6 and CXCL2 expressions in rat gingiva." (PMID 34024010, 2022). "Interestingly, orthodontic tooth movement did not further increase the periodontitis-induced CXCL2 gene expression in rat gingiva." (PMID 34024010, 2022).
influenza infection (17 papers, 2010 to 2024). "The suite of cytokines and chemokines assessed here, namely, TNF-α, IL-6, CCL2, CCL3, CXCL2 and IL-1β, are known to promote the inflammation caused by influenza at early stages of the infection phase, i.e. during the cytokine storm, and have been shown to underpin the pathology and morbidity." (PMID 23577160, 2013). "CCL3 and CXCL2 have also been shown to be involved in the recruitment of neutrophils in models of bacterial infection, and are both upregulated in influenza infection." (PMID 35601109, 2022). "In a different model of A. fumigatus superinfection following IAV infection, mice infected with influenza infection had decreased pulmonary concentrations of the neutrophil chemoattractants CXCL1 and CXCL2 following A. fumigatus challenge." (PMID 37681974, 2023). "Previous research has shown that inflammation-related factors (IL-1, TNF, CXCL1, CXCL2, S100A8, and S100A9) predominantly express in neutrophils, and neutrophils infiltration largely account for lethal influenza infection." (PMID 35495713, 2022). "Influenza infected NOX4 TG mice had decreased expression of CXCL10, CCL3, CXCL1 and CXCL2 three days post infection." (PMID 35601109, 2022). "Expression of the main neutrophil chemoattractants CXCL1, CXCL2, and CXCL5 were induced upon influenza infection, but were unaffected by IL-1β." (PMID 24918427, 2014). "The concentrations of the cytokines IL-1β, IL-6, TNF-α, CXCL1,CXCL2, CCL5, IFN-γ and IL-12p40 were evaluated in lung homogenates ofcontrol and Influenza infected mice." (PMID 21079759, 2010). "Furthermore, the levels of CXCL13 in the culture supernatants of influenza-infected macrophages were significantly decreased upon the addition of recombinant CXCL5, recombinant CXCL1 and CXCL2, or all the proteins combined." (PMID 34868067, 2021). "CXCL1 and CXCL2 expression was also induced in influenza-infected AMs; however, CXCL5 expression was not induced based on the detection of both mRNA and protein levels." (PMID 34868067, 2021). "In contrast to the findings obtained with the bacterial infection model, those obtained with the influenza-infected CXCL5-/- mice indicated that the levels of the major neutrophil chemoattractants CXCL1 and CXCL2 in the lungs were significantly decreased during the early infection stage." (PMID 34868067, 2021). "We confirmed the importance of CXCL2 expression in acute lung injury by transferring influenza-specific CD8+ T cells into transgenic mice lacking CXCR2." (PMID 24223177, 2013). "Similarly, CCL2 (Ccl2), a ligand for CCR2 that recruits CCR2+ inflammatory monocytes, as well as CXCL1 (Cxcl1), CXCL2 (Cxcl2), and CXCL5 (Cxcl5), which are ligands of CXCR2 that induce neutrophil infiltration in influenza-infected lungs, showed notable decreases in NOD.SCID mice." (PMID 37904257, 2023). "Unlike after adenovirus or influenza infections, AM from lungs that have recovered from pneumococcal pneumonia do not demonstrate elevated Cxcl2 or Il6 expression, whether of embryonic or adult HSC origin." (PMID 35133985, 2022). "Indeed, CXCL2 antagonism protected mice against respiratory IAV and pneumococcal infections, suggesting neutrophilia contributes to a worsening of the pathological condition during influenza infection." (PMID 35401240, 2022).
lung carcinoma (17 papers, 2012 to 2025). "In CUL4B-deficient settings within KRAS-mutated lung cancer cells, a derepression of CXCL2 expression ensues, which, through the CXCL2-CXCR2 signaling axis, augments MDSC recruitment." (PMID 40230836, 2025). "More recently, it was reported that Cxcl2 secretion increased in intra-tumor cells of Kras-mutated lung cancer mouse model, likely contributing to immune escape process of lung cancer cells." (PMID 34654834, 2021). "We employed mouse Lewis lung carcinoma cell line and human lung cancer cell line H460, which expressed CXCR2 on the surface and secreted CXCR2-associated chemokines, such as CXCL1, CXCL2, CXCL5 and MIF." (PMID 33814009, 2021). "Previous studies demonstrated that lung cancer with a KRAS mutation showed increased numbers of neutrophils through the expression of CXCL-1 and CXCL-2." (PMID 27483433, 2016). "Stage III cancers had significantly higher expression of CXCL2, CD69, CCR4, and TNFRsf13c, all of which have been implicated as potential therapeutic targets in other malignancies, or in the case of CCR4, poor prognosis in lung cancer." (PMID 35881197, 2023). "Differential expression analysis of epithelial cells showed a significant increase in expression of CXCL1, CXCL2, and HDGF in KRASG12D-driven lung cancer samples compared with non–KRAS-driven lung cancer." (PMID 39782689, 2025). "A study observed that the levels of CXCL1, CXCL2, CXCL5, CXCL7, and CXCL8 were higher in lung cancer compared to multiple other cancer types (breast, colorectal, esophageal, head and neck, and liver cancer)." (PMID 36612163, 2022). "In lung cancer, previous studies by others reported that NSCLC patients showed higher concentration of CXCL2 when compared with that of the protein in chronic obstructive pulmonary disease patients." (PMID 34654834, 2021). "Unlike our results, multiple studies have shown that CXCL2, CXCL3, CXC12, and CXC16 were highly expressed in lung cancer tissues and are essential for tumor growth." (PMID 35844446, 2022).